FAP (fibroblast activation protein alpha)
Diseases named in the same sentence as FAP in open-access papers (continued):
Sharing a sentence is not in itself a finding about the gene and the disease.
myocardial infarction (37 papers, 2018 to 2026). Gross necrosis of the myocardium, as a result of interruption of the blood supply to the area, as in coronary thrombosis. "A decline in systemic FAP concentrations was noted acutely after myocardial infarction, with the maximum C-reactive protein level independently being associated with a low FAP concentration." (PMID 40278373, 2025). "Circulating soluble fibroblast activation protein (FAP) is implicated in myocardial infarction, stroke, fibrosis and various cancers." (PMID 40690098, 2025). "Expression of the prolyl-specific serine peptidase fibroblast activation protein (FAP) is a hallmark of activated fibroblasts as seen after myocardial infarction." (PMID 37126137, 2023). "FAP is a membrane-associated serine protease expressed by activated fibroblast and is associated with myocardial damage and prognosis in myocardial infarction." (PMID 36568546, 2022). "In patients with acute ST-elevation myocardial infarction FAP concentrations decreased from baseline levels within 5 days after the event and higher reductions of FAP concentrations were associated with larger myocardial infarct size." (PMID 36568546, 2022). "Current cardiac fibrosis therapies primarily focus on targeting FAP, as demonstrated in key models like angiotensin II-induced fibrosis 4, 34 and myocardial infarction-induced fibrosis." (PMID 41356193, 2026). "It has also been shown that after acute myocardial infarction, FAP upregulation occurs in the infarct region and attached myocardium." (PMID 40278373, 2025). "In keeping with the in vivo data, FAP was observed in both the peri-infarct region and the remote myocardium of these patients with large myocardial infarcts." (PMID 39772364, 2025). "Fibroblast activation protein (FAP) is a prolyl-specific serine protease whose inhibition or vaccination has been shown to enhance cardiac repair following myocardial infarction (MI)." (PMID 40855978, 2025). "In a rat model of myocardial infarction (MI), cardiac FAP expression was significantly upregulated after MI, particularly in myofibroblasts in the area surrounding the infarction." (PMID 40607439, 2025). "Fibroblast activation protein α (FAP) is a serine protease expressed by activated fibroblasts in cardiovascular disease such as acute myocardial infarction and aortic stenosis as well as many cancers." (PMID 40690098, 2025). "It has been shown that genetic deletion of FAP leads to thicker scar formation and less ventricle dilatation following myocardial infarction, and immunomodulation with removal of FAP-expressing cells leads to the reversal of cardiac fibrosis." (PMID 39590809, 2024). "Data using FAP-targeted positron emission tomography and single-photon emission computed tomography in patients with acute myocardial infarction showed that the FAP expression exceeds the infarct region." (PMID 39590809, 2024). "Since FAP is also overexpressed in other disorders such as sclerosis, amyloidosis, and myocardial infarction, this study paves the way for FAP-targeted PET to guide personalized therapies for a broader spectrum of diseases." (PMID 39283414, 2024). "In mice myocardial infarction model, inhibition of FAP reduces ventricular fibrosis, improves cardiac function and promotes angiogenesis via stabilizing BNP." (PMID 37932744, 2023). "In resting fibroblasts, FAP is expressed at low levels but shows a steep increase in cases of myocardial infarction." (PMID 37869159, 2023). "The coexpression of CD90 and FAPα was also presented in Tilmann’s work in the case of human myocardial infarction." (PMID 38136590, 2023). "The dipeptidyl-peptidase fibroblast activation protein α (FAP) is a serine protease membrane glycoprotein with dipeptidyl-peptidase and collagenase properties, expressed by activated fibroblasts after myocardial infarction (MI) in animals and humans." (PMID 36568546, 2022).
myocardial infarction (continued). "Fibroblasts play a pivotal role in cardiac tissue remodeling and wound healing and the expression of FAP by activated cardiac fibroblasts increases after myocardial infarction and then declines over time." (PMID 35327325, 2022). "Fibroblast activation protein alpha (FAP) is upregulated in activated fibroblasts after myocardial infarction (MI), and alters fibroblast migration in vitro." (PMID 33667270, 2021). "Establishing the role of FAP-specific PET would also benefit from comparisons to other tracers that are mostly being investigated in the role of acute myocardial infarction such as the CXCR4 ligand 68Ga-pentixafor." (PMID 33606104, 2021). "Localized FAP activation has also been reported in other diseases that are followed by tissue remodeling, such as myocardial infarction." (PMID 30072500, 2019). "Finally, our histologic analysis confirmed the presence of FAP-positive fibroblasts in the infarct zone and peri-infarct zones of our patients who had sustained acute myocardial infarction." (PMID 39772364, 2025). "Concurrent application of the β + γ emitter with a novel radiotracer, e.g., the ligand of serine protease fibroblast activation protein (FAP), which is a biomarker of activated (myo)fibroblasts, will give a new advantage in assessment of post-myocardial infarction remodeling." (PMID 36959477, 2023). "Like CAFs, FAP expression is instead increased in activated fibroblasts in the case of tissue damage, remodeling, or inflammation, and, therefore, in benign conditions, such as wound healing, arthritides, and myocardial infarction." (PMID 35327325, 2022). "After myocardial infarction, FAP is strongly expressed compared with resting fibroblasts." (PMID 36072860, 2022). "With very broad potential applications of FAP in clinical medicine in the near future, further research using FAP radiotracers will allow for better understanding of fibroblast activation in acute coronary syndromes and healing responses after myocardial infarction." (PMID 40278373, 2025). "The role of FAP has been explored in various cardiac diseases, such as post-myocardial infarction (MI) fibrosis and fibrosis induced by angiotensin II administration." (PMID 40855978, 2025). "IHC revealed increased FAP expression in the MI group, with FAP being strictly localized to the area of myocardial infarction." (PMID 40430477, 2025). "It has been shown that after acute myocardial infarction, FAP upregulation occurs in the infarct region and attached healthy myocardium, suggesting that FAP may play a role not only in the replacement but also in reactive fibrosis, which occurs in other forms of atherosclerosis." (PMID 39590809, 2024). "FAP expression in the infarction and peri-infarction areas increase, peaking at 7 days after myocardial infarction (MI) in rats, and FAP-expressing fibroblasts were enriched in the ischaemic region of human hearts after MI." (PMID 37762974, 2023). "Our previous study has demonstrated the feasibility of noninvasive imaging of fibroblast activation protein (FAP)-expression after myocardial infarction (MI) in MI-territory in a rat model with 68Ga-FAPI-04-PET." (PMID 33860458, 2022). "Additionally, FAP has also been shown to be expressed by rheumatoid myofibroblastlike synoviocytes in patients with rheumatoid arthritis and osteoarthritis, atherosclerosis, and fibrosis, as well as in ischemic heart tissue after myocardial infarction." (PMID 29626120, 2018). "FAP PET can detect fibroblast activation and cardiac remodeling after acute myocardial infarction, with a potential predictive role of FAP uptake in the evolution of ventricular dysfunction." (PMID 39572227, 2025). "As with myocardial infarction, FAP positive segments comprised regions with and without late gadolinium enhancement and prolonged T1 relaxation time." (PMID 37126137, 2023). "A previous study of mice with myocardial infarction found that FAP knockout did not result in significant developmental defects." (PMID 37006278, 2023).
myocardial infarction (continued). "Together with preclinical data highlighting the role of FAP in myocardial infarction and FAP-specific PET of small animals, the application of FAP-specific PET in humans might provide more insights into the role of fibroblasts in acute as well as chronic heart disease." (PMID 33606104, 2021). "However, FAP expression is not cancer specific: many activated fibroblasts express FAP in wound healing and in nonmalignant diseases such as chronic inflammation, rheumatological diseases, myocardial infarction, lung fibrosis, or liver cirrhosis, among others." (PMID 34137945, 2021). "Finally, it has not escaped our notice that FAP-targeted drugs might find application in other diseases characterized by strong infiltration of activated fibroblasts such as organ fibrosis and myocardial infarctions 50-52." (PMID 32483418, 2020).
pancreatic ductal adenocarcinoma (37 papers, 2012 to 2026). An infiltrating adenocarcinoma that arises from the epithelial cells of the pancreas. "It is reported that both cancer and stromal cells undergo hypoxic necrosis rapidly in FAP depleted transgenic mice models of Lewis lung carcinoma or pancreatic ductal adenocarcinoma." (PMID 40438108, 2025). "For instance, Freed and colleagues identified two CTC subpopulations expressing epithelial cell adhesion molecule, EpCAM (CTCEpCAM), or fibroblast activation protein-alpha, FAPα (CTCFAPα), in pancreatic ductal adenocarcinoma (PDAC) patients." (PMID 38539545, 2024). "Further, the transition to malignant dysplasia in pancreatic ductal carcinoma was marked by changes in the expression pattern of FAP." (PMID 39579201, 2024). "It was reported that FAP was highly expressed in human pancreatic ductal adenocarcinoma (PDAC) cells." (PMID 36879039, 2023). "Recent studies identified αSMA+ and FAP+ CAFs with opposing functions in pancreatic ductal adenocarcinoma." (PMID 37033924, 2023). "FAP expression is elevated in a pancreatic ductal adenocarcinoma (PDAC) with immunohistochemistry showing FAP expression in >90% of PDACs." (PMID 34638433, 2021). "In this work, we analyze the expression levels and prognostic value of stromal tumor-infiltrating lymphocyte (CD4, CD8, and CD20) and cancer-associated fibroblast (Thy-1, FAP, and SMA) subpopulations in a cohort of pancreatic ductal adenocarcinoma patients." (PMID 34771664, 2021). "While FDG PET revealed a nodular lesion in the uncinate process, FAP-specific PET showed intense activity in the whole enlarged pancreas masking the lesion that was later confirmed as pancreatic ductal carcinoma." (PMID 33606104, 2021). "In pancreatic ductal adenocarcinoma, FAP-positive CAFs suppressed the effects of anti-PD-L1 treatment through CXCL12/CXCR4 signalling." (PMID 31462002, 2019). "Since this observation of immune suppression by the FAP α+/CD45+ stromal cell has been replicated in a transplanted model of pancreatic ductal adenocarcinoma, tumoral immune suppression is likely mediated by macrophages expressing FAP α and HO-1." (PMID 26985769, 2016). "A novel in vivo approach using mannose-modified mRNA lipid nanoparticles to target CD206 on M2 reprogrammed them into FAP-CAR-M, yielding decreases in activated cancer-associated fibroblast markers, collagen volume, and Col1a1 in a pancreatic ductal adenocarcinoma model." (PMID 41357209, 2025). "Moreover, depleting FAP+ fibroblasts in pancreatic ductal adenocarcinoma mice resulted in tumor shrinkage and the generation of robust antitumor immunity." (PMID 38558814, 2024). "Similarly, in a murine model of pancreatic ductal carcinoma, the depletion of FAP+ stromal cells potentiated the antitumor effects of anti-CTLA4 and anti-PD-L1 therapy." (PMID 38558814, 2024). "However, of note, one study showed bone marrow toxicity and lethal cachexia in mice bearing pancreatic ductal adenocarcinomas treated with FAP-targeting CAR-Tcells." (PMID 37333052, 2023). "We found that the median expression of FAP was highest in pancreatic ductal adenocarcinoma." (PMID 30726287, 2019). "Pancreatic ductal carcinoma (PDAC) belongs to the group of epithelial malignancies with a strong so-called “desmoplastic reaction”, leading to a prominent tumor stroma with cancer-associated fibroblasts that exhibit a marked overexpression of fibroblast activation protein (FAP)." (PMID 37345133, 2023). "Hence, the CXCL12 protein secreted by FAP-positive cells may direct the immunosuppression in human pancreatic ductal adenocarcinoma." (PMID 34681246, 2021).
pancreatic ductal adenocarcinoma (continued). "FAP imaging using [68Ga]Ga-FAPI PET/CT was further investigated in multiple sarcomas, gynecological tumors, and pancreatic ductal adenocarcinomas (PDAC)." (PMID 34681246, 2021). "Our results point to CD8 and FAP as potential prognostic biomarkers and demonstrate the heterogeneous expression pattern of CD200 in patients with pancreatic ductal adenocarcinoma." (PMID 34771664, 2021). "For instance, in a murine pancreatic ductal adenocarcinoma (PDAC) model, depletion of FAP-expressing CAFs is synergized with anti-PD-L1 immunotherapy." (PMID 32292502, 2020). "Also, in pancreatic ductal adenocarcinoma (PDAC), high FAP correlated with prolonged survival in some PDAC patients." (PMID 41410015, 2026). "This study investigated the role of four previously established fibroblast markers—FAP, PDGFR, periostin, and SMA—in a large study population of 321 patients with pancreatic ductal adenocarcinoma who underwent a surgical resection with a curative intension in one of the PANCALYZE study centers." (PMID 37046710, 2023). "Thus, a single protein, CXCL12, secreted from a single stromal cell type, the FAP α+ CAFs, explains the overriding immunosuppression by the FAP α+ cell in a model of human pancreatic ductal adenocarcinoma." (PMID 26985769, 2016). "However, although FAP depletion synergizes with anti-PD-L1 immunotherapy in preclinical models of pancreatic ductal carcinoma, sadly, FAP-targeted approaches have shown a lack of efficacy in clinical trials." (PMID 33946818, 2021).
pulmonary fibrosis (35 papers, 2014 to 2026). Chronic progressive interstitial lung disorder characterized by the replacement of the lung tissue by connective tissue, leading to progressive dyspnea, respiratory failure, or right heart failure. "Several groups have evaluated the utility of FAP PET for assessing pulmonary fibrosis associated with interstitial lung disease." (PMID 39572227, 2025). "Another caveat to consider is that the expression of FAPI is not limited to cancer-associated fibroblasts since FAP is expressed during remodeling of the extracellular matrix, which occurs during wound healing and in benign diseases like scleroderma and idiopathic pulmonary fibrosis." (PMID 41301015, 2025). "FAP is transiently expressed in specific fetal mesenchymal tissues and is also expressed in certain disorders associated with activated stroma, including wound healing, rheumatoid arthritis, osteoarthritis, cirrhosis and pulmonary fibrosis." (PMID 24520291, 2014). "Interestingly, ‘CCL19+ adventitial fibroblasts’ and ‘CCN3+ adventitial fibroblasts’ overexpressed fibroblast activation protein (FAP), a marker of activated fibroblasts and cancer-associated fibroblasts, including in canine idiopathic pulmonary fibrosis and canine lung cancer." (PMID 40114924, 2025). "As the number of fibroblast foci seems to be associated with the prognosis of patients with lung fibrosis, FAPα immunohistochemistry staining could help clarifying the prognosis of patients for whom a cryobiopsy or a surgical lung biopsy is necessary for diagnosis." (PMID 39364020, 2024). "Based on these considerations, it is necessary to develop a FAP-targeted cell therapy platform with greater clinical relevance for pulmonary fibrosis." (PMID 42123706, 2026). "The main novelty of this study lies in the use of primary human NK cells for FAP-targeted intervention in pulmonary fibrosis-related models." (PMID 42123706, 2026). "Based on this, research on FAP-centered engineered cell therapies is being gradually extended from settings such as myocardial fibrosis to pulmonary fibrosis." (PMID 42123706, 2026). "This study aimed to evaluate the diagnostic feasibility of [68Ga]Ga-FAP inhibitor (FAPI) and [18F]fluorodeoxyglucose ([18F]FDG) positron emission tomography (PET) for imaging pulmonary fibrosis in a mouse model." (PMID 41515504, 2025). "Nevertheless, 99mTc-H-PoFP2 demonstrated excellent in vivo FAP-targeting specificity in tumor-bearing mice and bleomycin-induced lung fibrosis animal models." (PMID 41471268, 2025). "Several fibroblast activation protein inhibitor (FAPI) based radiotracers have been developed for non-invasive diagnosis and quantitative evaluation of FAP expression in pulmonary fibrosis." (PMID 41471268, 2025). "In summary, our findings demonstrate that oleuropein alleviates bleomycin-induced pulmonary fibrosis in mice by directly binding to FAP-α, thereby interfering with the TGF-β/Smad pathway and regulating fibroblast autophagy and apoptosis." (PMID 41008517, 2025). "We evaluated the dynamics of fibrotic focus formation and the contribution of the main cell types, including FAPα+ cells, in this process using a murine model of bleomycin-induced lung fibrosis." (PMID 39768155, 2024). "In this review, we discuss the use of FAPα as a useful biomarker for the progression of lung fibrosis, by both its assessment in human fluids and/or its detection by imaging techniques and immunohistochemistry." (PMID 39364020, 2024). "Fibroblast activation protein (FAP), a protease overexpressed in many cancers, is upregulated in idiopathic pulmonary fibrosis in humans." (PMID 39188902, 2024). "On the contrary, preliminary data on the use of FAPα BALF concentrations as biomarker of lung fibrosis seem encouraging." (PMID 39364020, 2024). "[68Ga]Ga-FAPI-46 has demonstrated efficacy in assessing bleomycin-induced idiopathic pulmonary fibrosis by targeting highly expressed FAP cells, showing promising applications." (PMID 38888802, 2024).